HDAC10 (histone deacetylase 10)
Diseases named in the same sentence as HDAC10 in open-access papers (continued):
Sharing a sentence is not in itself a finding about the gene and the disease.
chronic myeloid leukemia (1 paper, 2025). "We speculate that hyperactive kinases, such as FLT3-ITD in AML cells or BCR-ABL in chronic myeloid leukemia cells and a subset of ALL cells, activate MYC and POLD1, and that this attenuates the cytotoxic effects of HDAC10 inhibition." (PMID 40301616, 2025).
cutaneous T-cell lymphoma (1 paper, 2025). "In this study, we explored the role of HDAC10 in Sézary syndrome, a leukemic and very aggressive subtype of cutaneous T-cell lymphoma." (PMID 39958888, 2025).
eczema (1 paper, 2022). "Bufexamac, an aryl alkanoic acid derivative and a nonsteroidal anti-inflammatory agent for the topical treatment of eczema and other inflammatory skin diseases, is a specific inhibitor of the deacetylases of histone types IIB (HDAC6 and HDAC10)." (PMID 35592524, 2022).
lymph node metastasis (1 paper, 2024). "Elevated HDAC10 expression significantly correlated with advanced pathological T-stage and metastasis but not with lymph node metastasis." (PMID 38733531, 2024).
lymphocytic leukemia (1 paper, 2025). "Artificially overexpressed HDAC10 in cultured chronic lymphoid leukemia (CLL) and mantle B cell lymphoma cells causes cell cycle arrest and apoptosis." (PMID 40301616, 2025). "We prove the efficacy of the HDAC10 inhibitor PZ48 in a Danio rerio larvae model and speculate that HDAC10 inhibitors might be prospectively used to treat aggressive lymphocytic leukemia." (PMID 40301616, 2025).
lymphoid tumor (1 paper, 2025). "Our results illustrate that a pharmacological inhibitor of HDAC10 evokes apoptosis specifically in lymphoid tumor cells." (PMID 40301616, 2025).
retinal degeneration (1 paper, 2017). Degeneration of the retina. "Our transcriptomic data also revealed an increase in a number of non-apoptotic pathway genes that have been implicated in retinal degeneration, such as a number of poly-ADP-ribose-polymerases (PARP9, PARP14, PARP15) and histone deacetylases (HDAC7, HDAC10, HDAC11)." (PMID 29263354, 2017).
rotator cuff tears (1 paper, 2022). "Based on the risk of being damaging and on the potential role in rotator cuff etiopathogenesis, three candidate genes for rotator cuff tears were prioritized: COL23A1, EMILIN3 and HDAC10." (PMID 36358266, 2022).
Sézary syndrome (1 paper, 2025). "Our findings demonstrate that HDAC10 plays a key role in the molecular background of Sézary syndrome, highlighting its importance in the cellular mechanisms of the disease." (PMID 39958888, 2025). "A series of functional assays was performed to determine the role of HDAC10 in Sézary syndrome cell lines." (PMID 39958888, 2025).
viral infection (1 paper, 2017). "It is evident that vEnv treatment led to downregulation of cellular HDAC10 and HDAC6 expression, and downregulation of HDAC10 by shRNA knock-down significantly enhanced HIV viral infection and/or replication, especially through facilitation of progeny virion infectivity." (PMID 28842659, 2017).
tumor (46 papers, 2015 to 2026). "Exploiting such tumor-associated functions of HDAC10 requires the identification of biomarkers for the anticancer activity of its inhibitors." (PMID 40301616, 2025). "The hypermethylation of this gene in EBV(+) DLBCL implies suppression of the HDAC10 pathway and loss of inherent tumor suppressive function." (PMID 41008837, 2025). "The analysis revealed that high HDAC10 expression is significantly associated with poorer patient outcomes (p = 0.0093), underscoring its potential role in promoting tumor progression and its value as a therapeutic target." (PMID 40657362, 2025). "The deletion of HDAC10 is also associated with maintenance of an immunosuppressive environment, characterized by high density of the tumor-supporting M2 macrophages." (PMID 39409979, 2024). "Deletion of HDAC-10 in knock-out tumor cells induces higher expression of SOX9 and genes associated with the TGF pathway, indicating a possible mechanistic association." (PMID 36263432, 2022). "More precisely, at least two studies revealed an association of HDAC-5 and HDAC-10 isoforms overexpression with higher tumor burden in NSCLC patients." (PMID 34441281, 2021). "Moreover, the underlying mechanisms of HDAC10 for affecting the tumor cells and the TME need to further elucidated at the cellular and molecular levels." (PMID 39237939, 2024). "Furthermore, we show loss of HDAC10 prevents both restoration of polyamine levels and growth rescue, implicating HDAC10 in supporting polyamine-associated tumor growth." (PMID 35988653, 2022). "Another work showed that productive autophagy with efficient autophagosome-lysosome fusion is dependent on HDAC10 and that depletion of HDAC10 enhances the sensitivity of tumor cells to chemotherapeutic agents such as doxorubicin." (PMID 40260239, 2025). "Chidamide inhibits the activity of HDAC3, HDAC1, HDAC3, and HDAC10 selectively, suppressing tumor cell proliferation and triggers tumor cell apoptosis effectively." (PMID 40963853, 2025). "Depending on cellular context, HDAC10 can induce both oncogenic and tumor suppressive effects across an array of human cancer types." (PMID 41008837, 2025). "Specifically, down‐regulation of HDAC10 in tumour cells and continued activity of FGF and VEGF signalling pathways in transformed SCLC highlighted tumour‐intrinsic changes as the primary drivers of resistance, rather than alterations of the TME." (PMID 40677104, 2025). "Beyond its roles in tumor cell survival and proliferation, HDAC10 also contributes to immune evasion." (PMID 40657362, 2025). "While HDAC10 gene can function as either an oncogene or tumor suppressor depending on cellular context, it has been reported to exert tumor-suppressive effects in B-cell lymphomagenesis." (PMID 41008837, 2025). "Research studies have demonstrated that HDAC10 contributes to tumor progression by exerting its epigenetic function and modulating distinct molecules and signaling pathways." (PMID 38733531, 2024). "The following colony-formation assay, EdU, and CCK8 experiments showed that overexpression of HDAC10 can promote the proliferation of tumor cells while knockdown of HDAC10 can significantly inhibit the process." (PMID 39237939, 2024). "In the present study, the HDAC10 level significantly increased in After Tumor, and it has been reported as an epigenetic target in several malignancies." (PMID 38136558, 2023). "According to the assessment upon the mice tumor tissues, overexpressed HDAC10 resulted in increased expression level of HDAC10 and decreased miR-223 expression levels." (PMID 35075362, 2022). "Here, we use CRISPR/Cas9-mediated HDAC10-knockout cell lines and HDAC10-specific inhibitors to investigate the contribution of HDAC10 in maintaining tumor cell proliferation." (PMID 35988653, 2022). "While HDAC class I and IV overexpression promotes the development of CSCs in lung cancer, HDAC-10 (class IIb) acts as a tumor suppressor by targeting CSCs." (PMID 36263432, 2022).
tumor (continued). "The results showed that the protein expression level of HDAC10 was significantly downregulated in tumor samples." (PMID 36172179, 2022). "Expression levels of HDAC10 in cancer patients are seen to correlate both favorably and unfavorably with patient prognosis, depending on tumor origin." (PMID 35988653, 2022). "Advanced tumor HDAC10 levels can be used as an indicator of resistance, and high HDAC10 levels indicate that the tumor will be resistant to chemotherapy." (PMID 36227941, 2022). "In this review, we focus our attention on the progress of studies on the role of HDAC10 in various tumors and non-tumor diseases." (PMID 33997894, 2021). "In metastatic cervical squamous cancer cells, HDAC10 serves a tumor suppressor role through the regulation of MMPs." (PMID 33997894, 2021). "Our studies suggest that HDAC10 is a potential target for therapeutic intervention to inhibit angiogenesis and tumor growth." (PMID 28977867, 2017). "The HDAC10-overexpressing cells produced significantly larger tumours than the control cells, and the HDAC10-knockdown cells produced significantly smaller tumours than the control cells." (PMID 27449083, 2016). "We found that tumours comprising HDAC10-overexpressing cells grew significantly faster than those comprising control cells." (PMID 27449083, 2016). "In the HDAC10-knockdown group, tumour initiation required more cell injections, and these tumours grew significantly more slowly than those initiated by the control cells." (PMID 27449083, 2016). "Other variants related to tumor biology included a homozygous BRAF p.V600E mutation in THJ-21T and heterozygous and homozygous frame-shift deletions of HDAC10 (p.H134Tfs) and CDKN2A (p.Q70Sfs), respectively, in THJ-29T." (PMID 26680454, 2015). "It is though unclear whether a pharmacological inhibition of HDAC10 ceases cancer cell growth, how this affects normal cells, and if there are particularly sensitive tumor cell subtypes." (PMID 40301616, 2025). "This may suggest the correlation between ACVR1C expression and HDAC10 modulation in SS and highlights the possible tumor suppressor nature of the activin signaling pathway." (PMID 39958888, 2025). "A study demonstrated that the expression of HDAC10 was significantly and positively correlated with the expression of PD-L1 in tumor cells, suggesting that HDAC10 may be involved in tumor immunity." (PMID 40302782, 2025). "Pathway enrichment and the experiments of EdU staining, CCK-8 assay, cell transwell migration and invasion assay and colony formation assay demonstrated that HDAC10 mediated the proliferation and metastasis of ccRCC cells and involved in reshaping the tumor microenvironment (TME) of ccRCC." (PMID 39237939, 2024). "In addition, IHC performed on 184 cases of ccRCC tissues and 108 cases of normal renal tissues using tissue microarrays (TMAs) showed that HDAC10 expression was primarily located in the cytoplasm of tumor cells and increased at advanced clinical stages." (PMID 39237939, 2024). "However, up-regulated HDAC10 reverses this process and makes tumor cells more responsive to chemotherapy." (PMID 33997894, 2021). "With further in-depth study, HDAC10 may serve as an essential anti-tumor target and contribute to clinical applications in the future." (PMID 33997894, 2021). "Its functions involve in DNA damage repair, gene transcription and autophagy, and HDAC10-mediated tumor cell proliferation, apoptosis, invasion, migration, angiogenesis, metastasis and immune regulation, laying the theoretical foundation for clinical application." (PMID 33997894, 2021). "In addition, positive HDAC10 expression is correlated with adverse clinical features, such as larger tumor size, poor tumor stage and more lymph node metastasis." (PMID 33997894, 2021). "Considering that M2 macrophages may secrete anti-inflammatory molecules and promote tumor activity, HDAC10 may accelerate tumor progression by increasing tumor inflammation." (PMID 33997894, 2021).
tumor (continued). "Most striking were the large distances seen between PAD14, HDAC10 or DOT1L to other genes in the benign tissue dataset, with only PADI4 remaining isolated in the tumor tissue, suggestive of new tumorigenic transcriptional networks involving HDAC10 and independently, DOT1L." (PMID 27863398, 2016). "These interactions not only anchor Periplocin within the active site of HDAC10 but also likely inhibit its catalytic activity, disrupting downstream epigenetic regulatory pathway, which may contribute to tumor suppression by halting cell growth and inducing apoptosis." (PMID 40657362, 2025). "Previous studies suggest that HDAC10 may regulate the development of multiple tumor types." (PMID 38733531, 2024). "For example, in KIRC patients with low expression of Purinergic genes, the use of HDAC inhibitors targeting HDAC8, HDAC10, and HDAC11 may help to inhibit the invasive and metastatic ability of tumor cells, which is closely associated with a good prognosis for patients." (PMID 38180750, 2024). "In our study, we found the expression level of HDAC10 was significantly negatively correlated with most immune cell types, including Tgd cells, iDC and NK cells, which implied HDAC10 may influence the tumor antigen expression, antigen process and impair the function of the innate immunity system." (PMID 39237939, 2024). "Therefore, the mechanism of HDAC10 in tumor metastasis must be characterized in more detail." (PMID 33997894, 2021). "Notably, several HDAC genes, such as HDAC4 and HDAC10, showed significant, focal copy number loss, which is consistent with the experimental evidence that certain HDAC genes may serve as tumor suppressors during tumorigenesis." (PMID 30760718, 2019). "Consistently, Western blot results demonstrated that, relative to the PBS, CuZCeP@NC, and Sono@NC groups, tumor tissues from the Sono@NAT10 group exhibited significantly lower NAT10 and SRSF2 expression, accompanied by a notable upregulation of HDAC10." (PMID 41144699, 2026). "By reducing the acetylation level of SRSF2 protein and activating HDAC10, Sono@NAT10 promotes M1 polarization, suppresses tumor progression, and strengthens immunotherapy." (PMID 41144699, 2026). "A molecular characteristic of such cells is that they require HDAC10 to maintain the expression of MYC and POLD1 (i.e., HDAC10ness in analogy to the BRCAness of certain tumor cells)." (PMID 40301616, 2025). "HDAC inhibitors as single agents, via modulation of HDAC1, HDAC3, HDAC8 and HDAC10 function, increased the expression of MHCA and decreased the expression of PD-L1, PD-L2 and ODC on tumor cells." (PMID 29137331, 2017). "The analysis of 33 tumours using multiple data sources from The Cancer Genome Atlas (TCGA) and the NCI-60 drug screening database revealed that most tumours exhibited lower levels of HDAC6 and HDAC10 compared to normal tissues." (PMID 39941046, 2025). "We identified several pathways that shifted during transformation, and the transformation might be promoted by epigenetic alterations (such as HDAC10, HDAC1, DNMT3A) within the tumor cells instead of within the tumor microenvironment." (PMID 39353908, 2024). "Six days after cell injection, the mice featuring tumours induced by HDAC10 overexpression exhibited successful tumour transplantation, while the control mice did not exhibit successful tumour transplantation until 10 days after cell injection." (PMID 27449083, 2016). "Interestingly, while the expression level of HDAC10 in the tumor samples failed to correlate with clinicopathological factors, HDAC10 expression in the adjacent normal tissue positively correlated with the presence of lymph node and/or distant metastases." (PMID 35988653, 2022). "However, the cellular functions and precise mechanisms by which HDAC10 inhibitors exert their anti-tumor effects are not completely understood." (PMID 29968769, 2018).
cancer (38 papers, 2015 to 2026). A tumor composed of atypical neoplastic, often pleomorphic cells that invade other tissues. "In cancer cells, HDAC10 has been implicated in facilitating autophagic flux, potentially by modulating the fusion of autophagosomes with lysosomes." (PMID 39958888, 2025). "Among the target genes of miR-1908-5p, PTEN, DNAJA4, ApoE, and HDAC10 were associated with cancer cell invasion and metastasis." (PMID 35463352, 2022). "HDAC4 and HDAC10 are Class II HDACs, which are associated with proliferation, migration, and invasion of a variety of cancers." (PMID 36172179, 2022). "Another recent study found that HDAC10 promotes cell autophagy, which is a major mechanism associated with cancer cell survival and drug resistance." (PMID 27449083, 2016). "Moreover, HDAC10-mediated pathways are closely associated with tumorigenesis and metastasis in various types of cancer." (PMID 32373519, 2020). "With the crystal structure of HDAC10 now in hand, the structure-based design of isozyme-specific inhibitors promises to open new avenues in studying the chemical biology of autophagy as well as the treatment of advanced-stage cancers in which this PDAC is implicated." (PMID 28516954, 2017). "In cancer cells, HDAC10 regulates Hsp70 activity, playing a significant role in promoting cell survival by supporting essential protective mechanisms." (PMID 39958888, 2025). "HDAC10 plays a multifaceted role in cancer progression, contributing to drug resistance, cell cycle regulation, and immune evasion." (PMID 40657362, 2025). "HDAC10 is known to play a crucial role in cancer progression by regulating cell proliferation, apoptosis, migration and invasion, and angiogenesis." (PMID 40091020, 2025). "HDAC10 was indicated to play a diverse role in regulating cancer cell survival by influencing autophagy and apoptosis, processes that are often interconnected in determining cell fate." (PMID 39958888, 2025). "The cytoplasmic localization of HDAC10, its involvement in cancer-related pathways, and its effects on cell growth, apoptosis, and autophagy make it a promising candidate for targeted therapy in SS." (PMID 39958888, 2025). "These pharmacological agents are instrumental in deciphering HDAC10’s biological functions, and offer promising avenues for novel cancer treatments." (PMID 38650694, 2024). "HDAC10’s involvement in critical cellular processes, such as cell proliferation, apoptosis, and autophagy, highlight its potential impact on cancer progression." (PMID 38650694, 2024). "We comprehensively evaluated HDAC10 expression in ccRCC by analyzing cancer cell lines and clinical samples, revealing a substantial upregulation of HDAC10 in ccRCC." (PMID 38733531, 2024). "Of note, although it has been reported that HDAC10 is expressed differently in various tumors, which was identified in our systematic analysis including 33 different cancer types, its exact role in the initiation and progression of KIRC is not yet clear." (PMID 39237939, 2024). "This has naturally led to a growing interest in targeting HDAC10 for cancer therapy, culminating in the development of selective HDAC10 inhibitors." (PMID 38650694, 2024). "In the case of HDAC10, there has been significantly more research carried out to examine the relationship to its activity in cancer." (PMID 37637416, 2023). "Another mechanism has also been suggested for the involvement of HDAC10 in inhibiting metastasis, as it is known to suppress matrix metalloproteases 2 and 9 expression that are critical for cancer cell invasion and metastasis." (PMID 37637416, 2023). "Numerous evidences in previous studies reported that HDAC10 was expressed at different levels in diverse kinds of cancers." (PMID 35075362, 2022).